CXCL5 (C-X-C motif chemokine ligand 5)
Diseases named in the same sentence as CXCL5 in open-access papers (continued):
Sharing a sentence is not in itself a finding about the gene and the disease.
mycobacterial infections (1 paper, 2017). "In ROS-deficient mice, we found a marked increase of CXCL5, a pulmonary epithelial cell-produced chemokine which may contribute to the recruitment of neutrophils early in mycobacterial infection." (PMID 29228045, 2017). "Additionally, pulmonary epithelial cells, the first-line pulmonary cells to be exposed to M. tb in TB infection, were recently found to secrete CXCL5, a potent neutrophil chemokine, in mycobacterial infections." (PMID 29228045, 2017). "Increased levels of chemokines, including CXCL5, CCL5 and CXCL1, were reported in previous mouse mycobacterial infection experiments." (PMID 29228045, 2017).
myocardial infarction (1 paper, 2021). Gross necrosis of the myocardium, as a result of interruption of the blood supply to the area, as in coronary thrombosis. "During the acute phase of myocardial infarction (MI) in the adult heart, resident macrophages recruit leucocytes (by secreting CXCL2 and CXCL5) and monocytes (by secreting CCL2) to the ischemic area." (PMID 33130914, 2021).
neuropathic pain (1 paper, 2016). Chronic pain caused by damage to nerve fibers. "Of the 47 investigated proteins, 21 (cathepsin S, CCL2, CCL4, CCL16, CFIII, CXCL5, cystatin B, E-Selectin, Fas/TNFRSF6, follistatin, GDF-15, GH, ICAM1, IL8, KLK5, MMP2, MMP9, P-Selectin, sortilin, TIMP4 and VEGF) were detectable by multiplex SP-PLA in ≥ 95% of the neuropathic pain patient samples." (PMID 26914813, 2016).
neuropathies (1 paper, 2022). "Immunomodulators activated by MMPs include IL-1β, CXCL5, and CXCL8, whose genes were upregulated in lesional PN skin and are implicated in inflammation and neuropathies." (PMID 36619628, 2022).
Paget disease (1 paper, 2022). A malignant neoplasm composed of large cells with large nuclei, prominent nucleoli, and abundant pale cytoplasm (Paget cells). "Moreover, CXCL5 has been describe to increase RANKL expression in Paget's disease in bone." (PMID 35933642, 2022).
Parkinson disease (1 paper, 2022). A progressive degenerative disorder of the central nervous system characterized by loss of dopamine producing neurons in the substantia nigra and the presence of Lewy bodies in the substantia nigra and locus coeruleus. "Interesting, CXCL5 and MARCO are both related to inflammation, while UCHL1 is a gene specific for Parkinson’s disease but also described in AD." (PMID 36012501, 2022).
periodontal disease (1 paper, 2023). "Furthermore, CXCL5, ADM, FGF9, AIMP1, STC1, and CDKN2A might have a significant impact on the development of HNSC caused by periodontal disease." (PMID 37675228, 2023).
polyp (1 paper, 2022). A usually exophytic mass attached to the underlying tissue by a broad base or a thin stalk. "However, CXCL5 and CHI3L1 were both increased in the subgroup of infection in both CRC and polyp patients." (PMID 35646113, 2022).
primary immunodeficiency (1 paper, 2021). "In particular, we detected that ZAP70 was enriched in primary immunodeficiency, TNFRSF4, and CXCL5 were enriched in cytokine-cytokine receptor interaction, CTSG was enriched in the renin-angiotensin system, and the CHRM2 and CTSG were enriched in neuroactive ligand-receptor interaction." (PMID 34133324, 2021).
relapsing-remitting MS (1 paper, 2023). "Elevated neutrophil-to-lymphocyte ratios, NETs, CXCL1, and CXCL5 are detected in blood samples of relapsing-remitting MS (RRMS) patients, but not other forms of MS." (PMID 36873885, 2023).
respiratory infection (1 paper, 2024). "In a different model of respiratory infection, CXCL5 has been reported to affect B lymphocyte accumulation in the lungs of influenza virus-infected mice by regulating the expression of the CXCL13 chemokine and orchestrating the antiviral innate and adaptive immune responses." (PMID 38448450, 2024).
respirovirus infection (1 paper, 2021). "Recently, in a SARS-CoV-2-infected hACE2 -transfected mouse model, we found it affects neutrophil chemotaxis in infected lungs during the early infection stage, which suggests that CXCL5 functions in respirovirus infection." (PMID 34868067, 2021). "In addition to its prominent role in regulating innate immune cell trafficking in pulmonary bacterial infection models, how is CXCL5 function in respirovirus infection, such as influenza virus infection, which requires an intricate network of innate and adaptive immune mechanism." (PMID 34868067, 2021).
retinopathy of prematurity (1 paper, 2023). A bilateral retinopathy characterized by neovascularization, scarring, retinal detachment, and eventually blindness. "CXCL3, VEGF, CXCL5, and other inflammatory mediators were increased in DR and retinopathy of prematurity." (PMID 36658547, 2023).
rosacea (1 paper, 2025). A chronic erythematous skin disorder that affects the face. "This aligns with evidence that IL-17A-neutralizing antibodies suppress CXCL5/CXCR2 axis activation in murine rosacea models, attenuating both inflammatory and fibrotic responses." (PMID 40474977, 2025).
sarcoma (1 paper, 2025). A usually aggressive malignant neoplasm of the soft tissue or bone. "It includes information on cytokines that have been poorly studied in sarcoma peripheral blood samples, such as IL-24, IL-27, CCL21, CXCL5, and CXCL14." (PMID 41008853, 2025). "Levels of IL-1β, IL-4, IL-6, CXCL5, CXCL12, CXCL14, MIF, IGF-1, TGFβ-1, and CCL21 were increased in one or more sarcoma cohorts compared with controls, and levels of IL-15 and IL-16 were significantly lower in one or more sarcoma cohorts compared to healthy controls." (PMID 41008853, 2025).
Sciatica (1 paper, 2024). Pain in the lower back and hip radiating in the distribution of the sciatic nerve. "For instance, several key chemokines including CCL2, CCL11, CXCL5, CXCL6, and IL-16 were positively associated with sciatica." (PMID 39015317, 2024).
spinal injury (1 paper, 2021). A injury that involves the vertebral column. "The levels of cytokines CXCL5, CCL11, CXCL11, IL10, TNFα, and MIF were different between patients with baseline American Spinal Injury Association Impairment Scale (AIS) grades of A or B, whilst IL2 (>2 fold) and MIP-3a (>6 fold) were significantly expressed in the cervical and thoracic regions." (PMID 33806460, 2021).
spondylolisthesis (1 paper, 2026). A condition in which there is forward displacement of a vertebral bone over the on below it. "IP MR identified risk-increasing associations for LSS (4E-BP1 and interleukin-4), spondylolisthesis (CXCL1, CXCL5, FGF-5, IL-15RA, and IL-4) and IDD (IL-20RA and IL-6), while IL-18 showed a protective association with IDD that remained robust after multiple-testing correction." (PMID 42317351, 2026).
stricture (1 paper, 2025). "MDK–NCL, CXCL5/6‐CXCR2, and TGFA–EGFR ligand–receptor pairs were enhanced in stricture tissues, mediating epithelial–stromal interactions." (PMID 39910700, 2025).
systemic lupus erythematosus (1 paper, 2025). An autoimmune multi-organ disease typically associated with vasculopathy and autoantibody production. "CXCL5, a chemokine involved in neutrophil recruitment, shows altered levels in systemic lupus erythematosus, but its role in ME/CFS requires further study." (PMID 40427027, 2025).
systemic vasculitis (1 paper, 2022). "CXCL1-3 and CXCL5 are expressed by M1 macrophages and control the recruitment of neutrophils during tissue inflammation, and BD is a systemic vasculitis featured by notable neutrophil infiltration, CXCL1-3 and CXCL5 might be the key chemokines produced by BD macrophages to over-attract neutrophils." (PMID 36333776, 2022).
T-cell lymphoma (1 paper, 2019). "Since intraperitoneal injection of bexarotene decreased expression of CCL22, CXCL5, and CXCL10 mRNA in EL4 mouse T-cell lymphoma, we hypothesized that serum levels of CCL22, CXCL5, or CXCL10 might be associated with response in CTCL patients treated with bexarotene." (PMID 31616630, 2019). "Since intraperitoneal injection of bexarotene decreased CXCL5 and CXCL10 mRNA expression in EL4 mouse T-cell lymphoma in vivo, we evaluated serum levels of these chemokines in patients with early and advanced CTCL." (PMID 31616630, 2019).
thymoma (1 paper, 2015). A neoplasm arising from the epithelial cells of the thymus. "In MG patients with versus without thymoma, 58 lncRNAs had 271 ‘cis’ genes upstream or downstream of their chromosomal position: lncRNA oebiotech_22652 had the highest number of ‘cis’ genes, whereas lncRNA oebiotech_12244 had 6 ‘cis’ genes(PPBP, CXCL1, CXCL5, PF4V1, PF4, and C14orf45)." (PMID 25889429, 2015).
thyroid cancer (1 paper, 2025). "The results demonstrated that CXCL5 expression exhibited statistically significant differences between thyroid cancer and normal thyroid tissue and displayed positive correlations with T stage, N stage, and AJCC stage." (PMID 40091357, 2025).
triple-negative breast carcinoma (1 paper, 2020). An invasive breast carcinoma which is negative for expression of estrogen receptor (ER), progesterone receptor (PR), and human epidermal growth factor receptor 2 (HER2). "Moreover, SERPINE1, CXCL5, and CXCL8 were found dramatically elevated in triple-negative breast cancer (TNBC) cell lines compared with non-triple-negative breast cancer (non-TNBC) cell lines." (PMID 33371368, 2020).
tuberculosis (1 paper, 2016). A chronic, recurrent infection caused by the bacterium Mycobacterium tuberculosis. "The IL-17RA pathway was recently shown to be critical in CXCL1 and CXCL5-mediated early neutrophil recruitment after M. tuberculosis H37Rv infection." (PMID 27853279, 2016).
uterine cancer (1 paper, 2019). Primary or metastatic malignant neoplasm involving the uterine corpus and/or the cervix. "A study in a mouse model of uterine cancer found that neutrophils largely resided within hypoxic foci, and the culture of uterine cancer cell lines in hypoxia led to the expression of potent neutrophil chemo-attractants; CXCL1, CXCL2, and CXCL5." (PMID 31461847, 2019).
vascular dementia (1 paper, 2025). A degenerative vascular disorder affecting the brain. "A variety of observational studies suggest a possible connection between C‐X‐C Motif Chemokine Ligand 5 (CXCL5) and vascular dementia (VaD), though the exact causal relationship is still uncertain." (PMID 40135623, 2025).
viral hepatitis (1 paper, 2023). An acute or chronic inflammation of the liver parenchyma caused by viruses. "For each etiology-based subgroup (NAFLD, ALD, viral hepatitis, and “other”), CXCL5, CXCL9, and CXCL10 were significantly elevated in HCC patients and might be used as etiology-independent HCC-discriminant chemokine panel." (PMID 36982370, 2023).
tumor (559 papers, 2007 to 2026). "In anti-PD1 therapy for GC, overexpression of CXCL5 recruits tumor-associated neutrophils via the CXCL5/CXCR2 axis, which is a key factor in driving immunosuppression." (PMID 39915459, 2025). "The NOTCH signaling pathway also modulates TGF-β and CXCL5 secretion to promote the infiltration of tumor-associated neutrophils, and reprograms metabolic processes, such as switching glycolytic processes, to induce tumor growth." (PMID 40863244, 2025). "The CXCL5/CXCR2 axis has been implicated in promoting tumor development, angiogenesis, and the activation of host cells." (PMID 39670859, 2025). "CXCR2, the receptor for CXCL3 and CXCL5, has been associated with promoting cellular processes such as tumor cell proliferation, migration, invasion, angiogenesis, lymphangiogenesis, and cellular senescence." (PMID 38365809, 2024). "CXCL5 is elevated in tumor tissues and is positively associated with lymphatic metastasis and tumor differentiation." (PMID 38281962, 2024). "Analysis of TCGA data showed that macrophage abundance was associated with CXCL5 expression in tumor tissues, suggesting an association between macrophages and CXCL5." (PMID 38642131, 2024). "In contrast, in CALB1-expressing tumors, transcription of the same mediators was minimal in cancer cells and instead was found in myeloid cells (CXCL2, CXCL8) and/or tumor-associated fibroblasts (CXCL5, CXCL6)." (PMID 37192000, 2023). "In patients with HCC, CXCL5 serum levels were associated with tumor progression, and levels of CCL20 and CXCL8 with macrovascular invasion." (PMID 36982370, 2023). "CXCL1 and CXCL5 activation; Loss of blood flow to the interior of the tumor induced by neutrophil accumulation." (PMID 35640930, 2022). "Statistically, Pearson’s r correlation analysis indicated a positive association between DDR1 and CXCL5 level in 3 cases of pancreatic patient tumor specimens (case 1: r = 0.4423; case 2: r = 0.4467; and case 3: r = 0.4166)." (PMID 34237033, 2021). "Increased levels of CXCL5 in bladder tumors, as well as in urine, were associated with tumor stage, grade and lymph node metastasis." (PMID 34572939, 2021). "SPP1+ and CXCL5+ Mφ (clusters 6 and 7) clusters were enriched in tumor tissues and therefore were designated as tumor‐associated macrophages (TAMs)." (PMID 34185431, 2021). "CXCL5 was involved in the interaction between cholangiocarcinoma cells and cancer-associated fibroblasts and inhibition of tumor-stromal interactions." (PMID 34194499, 2021). "C-X-C motif chemokine ligand 5 (CXCL5) is reported to contribute to the invasion of cancer cells, and its aberrant expression is associated with the cellular process of tumor pathology." (PMID 34603292, 2021). "Cxcl5 is a key local cue that recruits tumor associated macrophages (TAMs), which in turn promote a pro-tumorigenic environment." (PMID 33946495, 2021). "In the RENCA mouse model, blocking CXCR2, a receptor for IL-8 and CXCL5, with a combined use of an anti-PD-1 antibody caused a decrease in tumor weight." (PMID 34445235, 2021). "Conversely, within the same tumor we observed that regions of low DDR1 expression were associated with decreased CXCL5 expression (red arrow)." (PMID 34237033, 2021). "The association between preoperative serum CXCL5 levels and clinicopathological parameters (age, BMI, pathological grade, phimosis, histological subtype, tumor stage, and nodal status) was analyzed." (PMID 33458757, 2021). "In this study, we reported that the expression of CXCL5 was elevated in tumor tissues and positively associated with lymphatic metastasis and tumor differentiation." (PMID 32632106, 2020). "Expression of tumor-derived CXCL5 is associated with mutant Kras expression and regulated by tumor NF-kB activation." (PMID 33304355, 2020).
tumor (continued). "Researchers have observed that macrophage-driven efferocytosis of PCa in vitro activated Stat3 and NF-κB (p65) signaling to stimulate the expression of the pro-inflammatory cytokine CXCL5, whose deficiency reduced tumor progression." (PMID 32346605, 2020). "High expression of CXCL5 in tumor tissues was positively associated with an advanced T stage (p=0.036), positive lymph node metastasis (p=0.014) and a poor differentiation status (p=0.003) in 90 PDAC patients." (PMID 32201508, 2020). "For example, administration of Stat3 reduces skeletal metastatic tumor growth and decreases skeletal tumor size, and CXCL5-deficient mice inhibit tumor progression, providing a clue for designing additional successful therapies." (PMID 32346605, 2020). "Meanwhile, we revealed underlying hints for CXCL5's role in shaping immunosuppressive tumor microenvironment in PDAC." (PMID 32201508, 2020). "Our findings showed that CXCL5 was upregulated in GC and its upregulation was associated with lymphatic metastasis and tumor differentiation." (PMID 32632106, 2020). "Neutrophils can have significant anti-tumor activity Expression of CXCL1, CXCL2, and CXCL5 chemokine driven by hypoxia within the tumor microenvironment cause neutrophil recruitment to the tumor site." (PMID 32824655, 2020). "High CXCL5 expression in tumor tissues was significantly associated with the T3 stage, the N2 stage and a poor differentiation status." (PMID 32201508, 2020). "Conversely, the mRNA expression of S100A14, IL1A, CCL2, CXCL3 and CXCL5 in tumor tissues derived from S100A14-deficient mice was significantly reduced compared with those from their WT counterparts." (PMID 32483412, 2020). "In our study, we first reported that high CXCL5 expression in tumor tissues was associated with the increased infiltration of M2 polarized macrophages, neutrophils and IgG+ plasma cells." (PMID 32201508, 2020). "Serum CXCL12 levels were associated with nodal involvement while CXCL5 concentrations were associated with depth of tumor invasion and distant metastasis." (PMID 33182840, 2020). "Our previous findings confirmed that ICC cells recruit more tumor-associated neutrophils (TANs) to the tumor microenvironment, by secreting chemokines CXCL5." (PMID 31555597, 2019). "We found that CXCL5 staining was markedly stronger in tumor tissues and that it was positively associated with CD31 staining." (PMID 30792394, 2019). "In our previous study, we demonstrated that CXCL5 is overexpressed and is associated with invasion, migration, and advanced tumor stages in CRC2." (PMID 30792394, 2019). "While the CXCL2 expression is elevated in the stromal compartment, CXCL5 expression is associated with the mutant Kras status in tumor cells and regulated by NF-κB and in line upregulated in the tumor cells." (PMID 31561620, 2019). "Neutrophils are attracted by various ligands including CXCL1, CXCL2, CXCL5 to tumor site and play central roles as tumor-associated neutrophil (TAN) in tumor inflammation and development from initiation to metastasis." (PMID 30220913, 2018). "Mechanisms underlying the regulatory role of CXCL5 in tumorigenesis and tumor progression have been extensively investigated." (PMID 29743818, 2018). "Previously, we demonstrated that a high serum CXCL5 level is associated with advanced lymph node classification, distant metastasis and tumour progression in NPC patients." (PMID 29665837, 2018). "As the disease progresses, the influence of CXCL5 on tumor cells becomes the dominant cause of cancer." (PMID 28356111, 2017). "Cancer cells facilitate recruitment of tumor-associated neutrophils (TANs) by expressing various of chemokines and cytokines, including CXCL5, CXCL6, and CXCL839, along with ligands that recognize receptors such as CXCR2 expressed by TANs40." (PMID 28223716, 2017).